CRTC1 (CREB regulated transcription coactivator 1)
Diseases named in the same sentence as CRTC1 in open-access papers (continued):
Sharing a sentence is not in itself a finding about the gene and the disease.
ischemic stroke (2 papers, 2021 to 2024). A stroke disorder caused by obstruction of blood flow to the brain, due to thrombotic (local blood clot formation) or embolic (due to a blood clot or other material traveling from another site) event. "CRTC1 dysfunction is associated with memory deficiency caused by ischemic stroke, Alzheimer's disease, and LPS." (PMID 38353058, 2024). "Our findings showed that CRTC1 deficiency decreased miR-132/212 expression and aggravated mice neurological outcome after ischemic stroke." (PMID 34880207, 2021). "Strikingly, the CRTC1 KO mice showed an approximately twofold increase in ischemic stroke volume compared with WT mice." (PMID 34880207, 2021). "CRTC1 deletion led to the reduction of miRNA-132/212 expression in mice brain after ischemic stroke, significantly increased infarct volume, and aggravated BBB permeability with worsening neurological deficits." (PMID 34880207, 2021). "To reveal the CRTC1-miR-132/212 signaling in the acute ischemic stroke phase, in this work we generated and subjected CRTC1 knockout and wild-type mice to 60 min transient middle cerebral artery occlusion (MCAO)." (PMID 34880207, 2021). "To clarify the role of CRTC1 in ischemic stroke, we subjected both CRTC1 KO and WT mice to 60 min of MCAO and evaluated the infarct volume using TTC staining after 24 h." (PMID 34880207, 2021).
status epilepticus (2 papers, 2016). Status epilepticus is defined as a continuous seizure lasting more than 30 min, or two or more seizures without full recovery of consciousness between any of them. "Furthermore, CREB-regulated transcription coactivator 1 (CRTC1) has been shown to translocate into hippocampal nuclei following pilocarpine-induced status epilepticus." (PMID 27855659, 2016). "In a recent study in pilocarpine-induced status epilepticus, a murine model of temporal lobe epilepsy (TLE), the nuclear translocation of CREB-regulated transcription coactivator 1 (CRTC1), which is a key regulator of CREB activity, was regulated by calcineurin activity in hippocampal neurons." (PMID 27597899, 2016).
amyloid (1 paper, 2024). "An abnormal decrease in pCREB and nuclear CRTC1 is affiliated with reduced synaptic plasticity and occurs in AD as well as in animal models of amyloid pathology." (PMID 39707506, 2024).
Ataxia (1 paper, 2023). Ataxia refers to impaired coordination of voluntary muscle movement. "A subset of FS symptoms, such as dystonia, myoclonus, and ataxia, may be attributed to the downregulation of PLEKHG2, DST, ARX, AAAS, KCTD17, PRDM8, and CRTC1 in FS brains as these genes are downregulated in Q84Pfs-Het brains and play a role in these movement and muscle coordination 43–49." (PMID 37398410, 2023).
bone cancer (1 paper, 2018). A primary or metastatic malignant neoplasm affecting the bone or articular cartilage. "And, it is important to emphasize that interruption to the positive feedback regulation between CREB/CRTC1 and miR-132 can effectively relieve bone cancer pain." (PMID 29615865, 2018). "All above illustrates the positive feedback regulation between miR-132 and CREB/CRTC1 in the spinal cord contributes to the maintenance of bone cancer pain." (PMID 29615865, 2018). "p-CREB, CRTC1 and CREB-target genes (NR2B and miR-132) were up-regulated in a bone cancer pain model." (PMID 29615865, 2018).
colon adenocarcinoma (1 paper, 2022). "CRTC1 and its isoforms have been implicated in oncogeneses, such as colon adenocarcinoma and a non-CREB-mediated pathway." (PMID 36726909, 2022).
Down syndrome (1 paper, 2016). "Moreover, CRTC1 mRNA expression has been found to be decreased in other neurodegenerative conditions and brain diseases, such as frontotemporal lobar degeneration with progranulin mutations and Down syndrome." (PMID 27094739, 2016). "Interestingly, a significant decrease in CRTC1 mRNA levels was shown for CRTC1 transcript variant 1 (NM_015321) but not for CRTC1 transcript variant 3 (NM_001098482) in Down syndrome adult brain, which is in line with our present work." (PMID 27094739, 2016).
Hepatic steatosis (1 paper, 2016). Steatosis is a term used to denote lipid accumulation within hepatocytes. "Accordingly, Crtc1 deficient mice develop spontaneous hepatic steatosis in young age." (PMID 27869139, 2016). "Accordingly, genetic Crtc1 deficiency in mice induced spontaneous hepatic steatosis in young age." (PMID 27869139, 2016). "We report that the transcription cofactor CRTC1 confers broad spectrum protection against hepatic steatosis development." (PMID 27869139, 2016).
idiopathic scoliosis (1 paper, 2021). A scoliosis with no known cause. "Considering histochemical and physiological abnormalities in muscles of patients with idiopathic scoliosis, we suggested that CRTC1 may be the target gene of MIR4300 that may function in the curve progression." (PMID 33985553, 2021).
ischemia (1 paper, 2021). A hypoperfusion of the BLOOD through an organ or tissue caused by a PATHOLOGIC CONSTRICTION or obstruction of its BLOOD VESSELS, or an absence of BLOOD CIRCULATION. "To elucidate the functional role of miR-132/212 in the BBB in ischemia, we modeled the BBB in vitro, using a co-culture system of vascular endothelial cells (HUVECs) and neurons derived from CRTC1 KO or WT mice." (PMID 34880207, 2021).
Lewis lung carcinoma (1 paper, 2025). "CRTC1/Notch1-dysregulated Lewis lung carcinoma (LLC) cells were co-cultured with T cells to evaluate T cell activation and function." (PMID 40977688, 2025).
melanocytic neoplasm (1 paper, 2025). "Cutaneous melanocytic tumor with CRTC1::TRIM11 fusion (CMTCT) is a rare and recently recognized melanocytic neoplasm with fewer than 50 reported cases." (PMID 41536371, 2025).
memory impairment (1 paper, 2025). "The western blot results verified a significant decrease in the level of CRTC1 (p < 0.05) and p‐AMPK (p < 0.05) in both PFC and hippocampus, suggesting that CRTC1 and AMPK may play critical roles in aging‐induced memory impairment in the NOR task." (PMID 40285336, 2025).
respiratory infection (1 paper, 2024). "One clinical study showed that selectively inhibiting CRTC1 improved the immune function and reduced infection rates, particularly respiratory infection rates in elderly people." (PMID 38644501, 2024).
sarcoma (1 paper, 2026). A usually aggressive malignant neoplasm of the soft tissue or bone. "In one case, methylation profiling yielded a clear cell sarcoma score of 0.885, just below the confidence threshold, likely due to shared CREB-MITF pathway activation and the lack of a dedicated CRTC1::TRIM11 reference class." (PMID 42015602, 2026).
Sepsis (1 paper, 2024). Sepsis is defined as life-threatening organ dysfunction caused by a dysregulated host response to infection. "Our findings indicate that Crtc1 deficiency significantly ameliorates the sepsis-induced ALI symptoms, including decreased lung structure damage, reduced pulmonary vascular permeability, and lowered the levels of pro-inflammatory cytokines and chemokines." (PMID 38644501, 2024). "In summary, our data demonstrate that Crtc1 deficiency provided a protective effect against sepsis-associated ALI through activating Akt signaling pathway." (PMID 38644501, 2024). "Our findings reveal a detrimental role of CRTC1 in sepsis-induced ALI, and provide a novel and promising target to treat infection-associated ALI in clinic." (PMID 38644501, 2024). "Our study demonstrates that CRTC1 contributes to the pathogenesis of sepsis-induced ALI, while Crtc1 deficiency protects against ALI-associated inflammation and apoptosis both in vitro and in vivo." (PMID 38644501, 2024). "Our findings provide novel insights into the molecular function of CRTC1 in sepsis-induced ALI, and unveil potential strategies to treat ALI in clinic." (PMID 38644501, 2024). "Targeting CRTC1 would be a promising strategy to treat sepsis-induced ALI in clinic." (PMID 38644501, 2024). "Our study demonstrates that CRTC1 contribute to the pathological processes of inflammation and apoptosis in sepsis-induced ALI, and provides mechanistic insights into the molecular function of CRTC1 in the lung." (PMID 38644501, 2024).
tauopathies (1 paper, 2021). "Among the altered synaptic proteins, the synaptonuclear factor CRTC1 was recently linked to memory loss at early AD pathological stages, suggesting that altered synaptic CRTC1 may be involved in synapse pathology in tauopathies." (PMID 34593029, 2021).
thymic epithelial tumours (1 paper, 2026). "The MAML2 gene fusions (KMT2A::MAML2, YAP1::MAML2, and CRTC1::MAML2), which have been observed in a small subset of thymic epithelial tumours, were not identified in our cohort." (PMID 41344988, 2026).
cancer (80 papers, 2008 to 2026). A tumor composed of atypical neoplastic, often pleomorphic cells that invade other tissues. "In contrast, mutations in CRTC1 were frequently subclonal and considering both indels and SNVs, CRTC1 was indeed the cancer-critical gene with most frequent subclonal mutations (in 30% of the 27 tumors)." (PMID 28539123, 2017). "By exome sequencing, we identified novel, frequent frameshift mutations in four cancer-critical genes (CRTC1, BCL9, JAK1, and PTCH1)." (PMID 28539123, 2017). "Similarly, enhanced activity of Crtc1 is implicated in cancers." (PMID 37015912, 2023). "In conclusion, we identified CRTC1 as a promoter of tumor immune evasion and cancer progression in NSCLC via the Notch/Akt pathway." (PMID 40977688, 2025). "Exemplary cases include ncORFs in the cancer hallmark genes CREBBP, CRTC1, CSF3R, FGFR2, IKZF1 and MAP2K2 with peptide support in all but two of the analyzed cancer types." (PMID 37275273, 2023). "CRTC1 is a member of the CREB-regulated transcription coactivator (CRTC) family that plays a role in metabolism, aging, memory, and cancer." (PMID 40660393, 2025). "The CRTC family consists of three members, CRTC1, CRTC2, and CRTC3, which play important roles in metabolism, aging, and cancer." (PMID 34142658, 2021). "Three members of the CRTC co-activator family, CRTC1, CRTC2, and CRTC3, are expressed at varying levels in human lung epithelial and cancer cell lines." (PMID 34142658, 2021). "CRTC1 and CRTC2 exhibited predominantly faster migrating bands in all six LKB1-null cancer cells, consistent with enrichment of dephosphorylated forms in the setting of LKB1 deficiency." (PMID 34142658, 2021). "Apart from the four genes, other genes such as FBXL19, CSTF2, ZC3H11A, CRTC1 and MAGI3 influenced the formation and progression of human cancers with either carcinogenic or tumor-suppressive function." (PMID 30640723, 2019).
tumor (69 papers, 2010 to 2026). "In 60-80% of cases, this tumor is associated with a specific genetic fusion CRTC1 or CRCT3::MAML2, which provides a molecular signature for diagnosis, but also has prognostic value, as MAML2-positive tumors are associated with a much better survival rate." (PMID 39677248, 2024). "IHC results demonstrated that CRTC1 knockdown amplified the reduction in PD-L1 expression induced by atezolizumab, whereas Notch1 overexpression elevated PD-L1 expression in tumor tissues." (PMID 40977688, 2025). "Collectively, these data demonstrate that CRTC1 promotes tumor growth and PD-L1 expression in vitro through the Notch1/Akt pathway." (PMID 40977688, 2025). "We found that CRTC1 overexpression in tumor cells upregulates PD-L1, suppresses IFN-γ and IL-2 production, reduces CXCL10/11 secretion, and impairs T-cell cytotoxicity." (PMID 40977688, 2025). "In this study, we revealed that CRTC1 knockdown amplifies anti-PD-L1 tumor immunity via the Notch1/Akt pathway, improving atezolizumab efficacy and response rates." (PMID 40977688, 2025). "In vitro, CRTC1 overexpression promoted tumor cell growth, migration, invasion, and T cell immunosuppression." (PMID 40977688, 2025). "H&E staining of LLC tumors revealed enhanced tumor cell death, while IHC and Western blot confirmed PD-L1 downregulation and reduced CRTC1 protein levels in treated tumors, respectively." (PMID 40977688, 2025). "CRTC1 knockdown potentiated the therapeutic efficacy of atezolizumab, evidenced by xenograft tumor regression, increased CXCL10/11 expression, and elevated serum concentrations of IFN-γ and IL-2." (PMID 40977688, 2025). "CRTC1 knockdown enhanced atezolizumab’s anti-tumor effects, reducing tumor size, weight, and volume and increasing tumor cell death." (PMID 40977688, 2025). "In vivo data revealed that CRTC1 overexpression attenuated atezolizumab efficacy, whereas CRTC1 knockdown synergistically enhanced tumor suppression." (PMID 40977688, 2025). "Combining CRTC1 knockdown with atezolizumab synergistically enhanced anti-tumor T cell immunity, achieving the most significant tumor regression in xenografts." (PMID 40977688, 2025). "Atezolizumab increased tumor-infiltrating T cells, augmented by CRTC1 knockdown but blocked by Notch1 overexpression." (PMID 40977688, 2025). "Mechanistically, CRTC1 interacted with Notch1 to activate the Notch1/Akt pathway, stimulating PD-L1 upregulation, thereby facilitating tumor immunosuppression and growth." (PMID 40977688, 2025). "In LLC cells, CRTC1 upregulated tumor cell PD-L1 expression, suppressed T cell-derived IFN-γ and IL-2 production, diminished endogenous CXCL10/11 secretion, and impaired T cell proliferation and cytotoxicity." (PMID 40977688, 2025). "Given the critical role of T cell-mediated immunosuppression in NSCLC tumorigenesis, we established a tumor-T cell co-culture system to evaluate how tumor cell CRTC1 modulates T cell survival and cytotoxic function." (PMID 40977688, 2025). "Given the established roles of Notch1 in NSCLC proliferation, migration, and tumor immunity, along with its capacity to induce Akt phosphorylation (p-Akt), we investigated the involvement of the Notch1/Akt pathway in CRTC1-mediated regulation." (PMID 40977688, 2025). "ACTIN::MITF- and MITF::CREM-rearranged tumors are categorized as melanocytomas in the melanocytic tumors chapter while neoplasms with CRTC1::TRIM11 fusions are classified as malignant soft tissue tumors with uncertain differentiation." (PMID 39264472, 2024). "Distinction between the two is crucial, as Cutaneous melanocytic tumors with CRTC1:TRIM11 fusion is typically a low-grade neoplasm with good prognosis." (PMID 39420989, 2024). "Overall, the pathogenesis of SGCs has remained unclear, except for cases harboring tumor-specific recurrent chromosomal translocations that result in the formation of fusion genes, such as CRTC1 [MECT1]-MAML2 in MEC or MYB-NFIB in ACC." (PMID 36538240, 2023).
tumor (continued). "Earlier, several studies have revealed that a favorable prognosis is associated with CRTC1/3-MAML2 gene rearrangements in younger people, and with a tumor of low to intermediate grade." (PMID 36831055, 2023). "Cutaneous melanocytic tumor with CRTC1::TRIM11 fusion (CMTCT) is a newly described neoplasm that falls into the broad category of diagnostically challenging dermal proliferations with melanocytic differentiation." (PMID 34943200, 2021). "Collectively, our findings further emphasize previous observations from smaller series of MECs that the presence of the CRTC1/3-MAML2 fusion is associated with favorable clinical features, low-grade tumor histology, and a good prognosis." (PMID 34231055, 2021). "By using COX-2 inhibitors such as niflumic acid (NS-398), tumor growth was reduced in CRTC1+/LKB1− cases." (PMID 34199169, 2021). "Further investigation was conducted to determine whether the effects of tumor cell CRTC1 on T cell survival and cytotoxic capacity are mediated through the Notch1/Akt signaling pathway." (PMID 40977688, 2025). "This study investigates the involvement of CRTC1 in tumor immunity." (PMID 40977688, 2025). "Degradation of LAMP2a, PRDX1, and CRTC1 to promote pro-tumor activation of macrophages." (PMID 38370407, 2024). "Notably, CRTC1 overexpression reversed the protective effects of atezolizumab on tumor growth." (PMID 40977688, 2025). "Interrogation of TCGA datasets revealed concurrent upregulation of CRTC1 and PD-L1 (CD274) in NSCLC tumor specimens." (PMID 40977688, 2025). "Under atezolizumab treatment, CRTC1 overexpression in LLC tumors accelerated tumor growth, reduced tumor cell death, and upregulated PD-L1." (PMID 40977688, 2025). "LAMP2a degradation leads to the promotion of tumor-activating macrophages by degrading peroxiredoxin 1 (PRDX1) and CREB-regulated transcription coactivator 1 (CRTC1)." (PMID 38370407, 2024). "Previous studies have reported that the CRTC1/MAML2 fusion protein induces the activation of the Notch signaling pathway in the MEC, resulting in enhanced cell proliferation and tumor development." (PMID 35012286, 2021). "M2-like macrophage activation, immunosuppressive tumor microenvironment, and tumor growth were reversed by inhibiting LAMP2A, whose targets were found to be peroxiredoxin 1 (PRDX1) and CREB-regulated transcription coactivator 1 (CRTC1)." (PMID 33990205, 2021). "The absence of CRTC1/Notch conditional knockout mice limits our ability to dissect NSCLC tumor-induced immunosuppression." (PMID 40977688, 2025). "In vitro data revealed that CRTC1 in NSCLC cells upregulates PD-L1 by directly targeting the Notch1/Akt signaling pathway, thereby suppressing T-cell survival and cytotoxic activity, ultimately triggering tumor reprogramming in NSCLC cells." (PMID 40977688, 2025). "Worse overall survival was associated with higher pT stage, higher TNM stage, residual tumors, greater tumor size, high grade tumor histology, and absence of CRTC1::MAML2 fusion." (PMID 38067300, 2023). "CRTC1 potentiates the cAMP/CREB (transcription factor that binds to DNA sequences “cAMP response elements”) intracellular signaling pathway, which promotes tumor development." (PMID 34199169, 2021).
metabolic disorders (5 papers, 2016 to 2025). "The biological functions of CRTC1 and metabolic phenotypes of Crtc1 deficient mice uncovered in this work support the view that CRTC1 confers broad spectrum protection against the development of metabolic disorders." (PMID 27869139, 2016). "Collectively, these findings demonstrate the existence of an intriguing double-negative feedback loop between CRTC1 and miR-34a in the liver, in which CRTC1 protects against metabolic disorders in the liver, at least in part, by suppressing aberrant expression of its own inhibitor, miR-34a." (PMID 27869139, 2016).
neurodegenerative disease (3 papers, 2016 to 2021). A disorder of the central nervous system characterized by gradual and progressive loss of neural tissue and neurologic function. "CRTC1 has been implicated in several neurodegenerative diseases already." (PMID 27034888, 2016). "Like CRTC1, PSF/SFPQ also has been implicated in several neurodegenerative diseases already." (PMID 27034888, 2016).
CRTC1 also shares sentences with these, for which no sentence is quoted: breast carcinoma (11 papers); epilepsy (6); diabetes (5); infection (5); colorectal cancer (4); Mucoepidermoid carcinoma of the salivary glands (4); oesophageal adenocarcinoma (4); cyst (3); influenza (3); ovarian carcinoma (3); Parkinson disease (3); renal carcinoma (3); renal cell carcinoma (3); Tuberous Sclerosis Complex (3); acute lymphoblastic leukemia (2); autism (2); Barrett esophagus (2); cardiomyopathies (2); cardiovascular disease (2); Cognitive impairment (2); diabetic kidney disease (2); Friedreich ataxia (2); hepatocellular carcinoma (2); Hypertension (2); immune dysfunctions (2); Kidney Cyst (2); lung carcinoid (2); multiple myeloma (2); neuroblastoma (2); Ovarian cyst (2).
A further 72 diseases each share a sentence with CRTC1 in 2 papers or fewer.